MSN (moesin)
Diseases named in the same sentence as MSN in open-access papers (continued):
Sharing a sentence is not in itself a finding about the gene and the disease.
osteosarcoma (2 papers, 2016 to 2023). A usually aggressive malignant bone-forming mesenchymal neoplasm, predominantly affecting adolescents and young adults. "Phosphatydil inositol bisphosphate (PIP2), belonging to the Phosphoinositide (PI) signal transduction pathway, was related to the regulation of ezrin, an ezrin–radixin–moesin protein involved in metastatic osteosarcoma spread." (PMID 27026853, 2016). "In osteosarcoma studies, it is reported that the transcript levels of ENO1, MSN, and HSP90AB1 were higher in osteosarcoma tissues than in normal tissues." (PMID 37894284, 2023).
ovarian carcinoma (2 papers, 2022 to 2024). A malignant neoplasm originating from the surface ovarian epithelium. "The treatment of ovarian cancer cells with LPA also promotes O-GlcNAcylation of ezrin–radixin–moesin (ERM) cytoskeletal proteins, and although the exact mechanism is not entirely understood, LPA-induced activation of ERM suggests the role of LPA in the adhesion and migration of ovarian cancer cells." (PMID 38607068, 2024).
papillary thyroid carcinomas (2 papers, 2013 to 2022). "ELISA assays and WB analysis confirmed the increase of LDHB, Moesin, and ANXA1 in pre-surgical FNA of thyroid papillary cancer." (PMID 24023790, 2013).
Parkinson disease (2 papers, 2022 to 2025). A progressive degenerative disorder of the central nervous system characterized by loss of dopamine producing neurons in the substantia nigra and the presence of Lewy bodies in the substantia nigra and locus coeruleus. "Here, we found that the most common Parkinsonism gene mutation, LRRK2 G2019S, enhances the phosphorylation of the ERM proteins (Ezrin, Radixin, and Moesin), components of the perisynaptic astrocyte processes in a subset of cortical astrocytes." (PMID 39253496, 2025).
polyarteritis nodosa (2 papers, 2021 to 2023). Polyarteritis nodosa (PAN) is a rare, clinically heterogeneous, rheumatologic disease characterized by necrotizing inflammatory lesions affecting small- and medium-sized blood vessels. "Anti-phosphatidylserine-prothrombin complex (anti-PSPT) antibodies and anti-moesin antibodies are present in patients with polyarteritis nodosa (PAN)." (PMID 38022020, 2023).
renal carcinoma (2 papers, 2012 to 2021). A carcinoma arising from the epithelium of the renal parenchyma or the renal pelvis. "Here, we present evidence that TMIGD1 binds to ERM family proteins (moesin and ezrin), regulates the stability of microtubules and modulates cell migration in renal cancer cells, implicating TMIGD1 as a potential cancer therapeutic target." (PMID 34503512, 2021). "For example, the expression status of TMIGD1 in human cancers, such as colon and renal cancers, could determine whether moesin and ezrin function as pro- or anti-tumorigenic factors." (PMID 34503512, 2021). "An increase of CD44 protein was observed in Caki-1 renal cancer cells following hypoxia, which was attributed to the Rho kinase-mediated activation of ERM (Ezrin, Radixin, Moesin) proteins during hypoxia, since ERM proteins are associated with the cytoplasmic domain of CD44." (PMID 22937154, 2012).
thyroid cancer (2 papers, 2019 to 2022). "Incubating NTHY cells with EVs isolated from thyroid cancer cell lines did not affect the Alix, Moesin and Radixin expression (data not shown)." (PMID 35328683, 2022).
Ureteral obstruction (2 papers, 2014 to 2015). Obstruction of the flow of urine through the ureter. "The levels of Alpha-actinin-1 and Moesin in urine were increased 1 week after unilateral ureteral obstruction, a result consistent with western blot results of Alpha-actinin-1 and Moesin in kidney tissue." (PMID 25791774, 2015). "Rat model of unilateral ureteral obstruction (UUO) was established and renal moesin was examined by immunohistochemistry." (PMID 25406076, 2014).
viral infection (2 papers, 2019 to 2021). "Similar to ezrin and moesin, an increased level of radixin expression has been observed in many tumor tissues and it has also been implicated in the viral infection process for several viruses." (PMID 31018575, 2019). "Consistent with a role in immunodeficiency, there are a number of reports linking moesin to roles in viral infection including measles, HIV and hepatitis C." (PMID 31018575, 2019). "This study demonstrated that the synergistic effect between DENV2 infection and TNF-α induction could demolish moesin expression, redistribute vinculin, and reorganize the actin cytoskeleton during virus infection." (PMID 34696472, 2021).
Airway obstruction (1 paper, 2024). Obstruction of conducting airways of the lung. "The exact mechanism of how moesin is involved in the process of airway obstruction in LAM remains unclear." (PMID 38267973, 2024).
autoimmune myocarditis (1 paper, 2022). Autoimmune myocarditis is an autoimmune disease that affects the heart. "Moesin also promotes monocyte transendothelial migration and was found to be upregulated in cardiomyocytes isolated from hearts with experimental autoimmune myocarditis." (PMID 35563680, 2022).
biliary tract cancer (1 paper, 2017). "Besides the mutation in MSH6, we identified 3 more mutations affecting genes described in cancer, but only rarely reported in biliary tract cancer (≤ 2%; SRC, MSN, PTPRC)." (PMID 28146430, 2017).
bladder tumors (1 paper, 2013). "The proteomic approach identified differential expression of proteins previously linked with aggressive clinical outcome in bladder tumors: gelsolin, moesin, Ezrin, caveolin, Filamin A." (PMID 23308193, 2013).
cardiac hypertrophy (1 paper, 2022). "In accordance with these findings from cell culture and animal studies, we can describe the association between higher serum levels of DHT, increased moesin and vimentin expression levels, and higher degree of cardiac hypertrophy and fibrosis in patients with severe AS." (PMID 36206048, 2022). "As we cannot demonstrate a causal relationship between DHT and cardiac hypertrophy and/or fibrosis, we might, however, hypothesize a DHT-mediated increase in moesin and vimentin expression, which in turn might be associated with LVH and fibrosis." (PMID 36206048, 2022).
cervical intraepithelial neoplasia (1 paper, 2010). "The moesin staining in normal cervical samples (NC) and cervical intraepithelial neoplasia (CIN) samples was weak, which average staining score was 2.2 ± 0.92 and 2.6 ± 1.44, respectively." (PMID 20429915, 2010).
clear cell carcinoma (1 paper, 2012). "We observed an association between MSN+ staining and tumor grade, and serous and clear cell carcinoma subtypes (p < 0.001 each)." (PMID 22272721, 2012).
Cognitive impairment (1 paper, 2018). Abnormal cognition is characterized by deficits in thinking, reasoning, or remembering. "Therefore, an approach that inhibits AGEs-RAGE induced activation of RhoA/ROCK/moesin signaling pathway is expected to attenuate the cerebral microangiopathy and thus prevent the cognition impairment in T2DM." (PMID 29867568, 2018). "In conclusion, the present study demonstrates that BSHX prescription effectively improves diabetes-induced cognitive impairment and cerebral microangiopathy through inhibition of AGEs-RAGE induced expression of RhoA/ROCK/moesin signaling pathway." (PMID 29867568, 2018).
colorectal adenocarcinoma (1 paper, 2021). The most common type of colorectal carcinoma. "We initially assessed the gene expression levels of PD-L1, ezrin, radixin, and moesin in LS180 cells and Caco-2 cells which is also a representative human colorectal adenocarcinoma cell line and was used for comparison with LS180 cells." (PMID 34577564, 2021).
complication (1 paper, 2016). Any disease or disorder that occurs during the course of, or because of, another disease, treatment, or procedure. "This study first aimed to explore the role of moesin in altered endothelial function during the development of diabetic vascular complications." (PMID 26956714, 2016). "The complex pro- or anti-angiogenic conditions during the development of diabetic vascular complications suggest that moesin might be a potential therapeutic target in angiogenesis." (PMID 26956714, 2016).
cytomegalovirus infection (1 paper, 2021). A herpesvirus infection caused by Cytomegalovirus. "An association between antibodies against moesin, which is expressed in the microvilli of Schwann cells at the nodes of Ranvier, and AIDP has been suggested after cytomegalovirus infection." (PMID 33917929, 2021). "An association between antibodies against moesin, which is expressed at the microvilli of the Schwann cells at the nodes of Ranvier, and AIDP following cytomegalovirus infection has been suggested." (PMID 33917929, 2021).
dengue virus infection (1 paper, 2021). "A low expression of moesin, alterations to actin stress fibers, and a dot-like structural formation of vinculin are responsible for the cellular permeability changes of human ECs during dengue virus infection and TNF-α induction." (PMID 34696472, 2021).
diabetic kidney disease (1 paper, 2021). Progressive kidney disorder caused by vascular damage to the glomerular capillaries, in patients with diabetes mellitus. "In conclusion, our data indicate that OCTN1 can have a role in the progression of interstitial fibrosis under oxidative stress via moesin expression in diabetic kidney disease." (PMID 33907247, 2021).
Down syndrome (1 paper, 2023). "Among the interactors with high proximity, Moesin (Msn) is a protein that was up-regulated in the 5xFAD mice and was observed in microglia in non-demented and AD cells, co-localizing with Aβ in amyloid plaques in AD (late and early onset), as well as in Down syndrome." (PMID 37174641, 2023).
ductal breast carcinoma in situ (1 paper, 2020). A carcinoma entirely confined to the mammary ducts. "The data showed that p-Moesin level was significantly higher in ductal breast carcinoma in situ than those in adjacent normal tissues." (PMID 33292278, 2020).
emphysema (1 paper, 2022). "This is also suggestive of the role of MSN mutations in recurrent childhood pulmonary diseases and resulting emphysema, potentially through the modulation of alveolar structure and its effect on pulmonary inflammation." (PMID 36119109, 2022).
ependymal tumor (1 paper, 2015). A group of neoplasms which arise from the ependymal lining of the cerebral ventricles and from the remnants of the central canal of the spinal cord. "The immunohistochemical of ependymal tumors showed a unique expression of NHERF1 and some NHERF1-associated molecules, such as moesin, in microlumens that represent precursor polarized membrane structures retained by neoplastic ependymal cells." (PMID 25775275, 2015). "In ependymal tumors, NHERF1 expression was retained in polarized membrane structures, such as microlumens, rosettes and canals, where it co-localized with some of its ligands, such as moesin and PTEN." (PMID 25775275, 2015).
epilepsy (1 paper, 2024). A brain disorder characterized by episodes of abnormally increased neuronal discharge resulting in transient episodes of sensory or motor neurological dysfunction, or psychic dysfunction. "For instance, the miRNA rno-let-7c-5p is dysregulated in human epilepsy and inferred mRNA targets present in multiple other resources include Cux1 (Cut like homeobox 1), Il1a (Interleukin 1 Alpha), Msn (Moesin), Nat8l (N-acetyltransferase 8 like) and Wapl (WAPL cohesin release factor)." (PMID 38961125, 2024).
Fibroadenoma (1 paper, 2008). A benign tumor of the breast characterized by the presence of stromal and epithelial elements. "Similar to normal breast tissue, in breast fibroadenomas (FAD) moesin and P-moesin were prominently located at the cell membrane of epithelial elements, along with occasional stromal and myo-epithelial cells." (PMID 18493596, 2008).
glaucoma (1 paper, 2023). Increased pressure in the eyeball due to obstruction of the outflow of aqueous humor. "Moreover, the regulation of MSN phosphorylation is controlled by Rho-associated protein kinases (ROCK), and specific ROCK inhibitors (e.g., Netarsudil), in turn, were currently launched as promising glaucoma medications." (PMID 37509196, 2023). "In addition, we also identified the cytoskeleton-regulating protein moesin (MSN) with high abundance in CDR1-treated retinae compared to CTRL, whose phosphorylation state was also associated with dysfunction of the blood-retina barrier in an experimental glaucoma model." (PMID 37509196, 2023).
glomerulonephritis (1 paper, 2021). A renal disorder characterized by damage in the glomeruli. "Moesin was chosen for further study based on its reported contribution to glomerulonephritis, association with the slit diaphragm, participation in actin remodeling, and presence in glomerular mesangial cells, endothelial cells, and epithelial cells." (PMID 33669337, 2021).
head and neck squamous cell carcinoma (1 paper, 2018). A squamous cell carcinoma that arises from any of the following anatomic sites: lip and oral cavity, nasal cavity, paranasal sinuses, pharynx, larynx, and salivary glands. "The authors affirmed that moesin expression was significantly associated with head and neck squamous cell carcinomas progression." (PMID 29310601, 2018).
influenza (1 paper, 2017). An acute viral infection of the respiratory tract, occurring in isolated cases, in epidemics, or in pandemics; it is caused by serologically different strains of viruses (influenzaviruses) designated A, B, and C, has a 3-day incubation period, and usually lasts for 3 to 10 days. "Our previous study also provided evidence for the involvement of Rho/ROCK and PKC pathways in influenza-induced hyperpermeability in microvascular cells via phosphorylating Ezrin/Radixin/Moesin (ERM)." (PMID 29059211, 2017).
kidney cancer (1 paper, 2021). Primary or metastatic malignant neoplasm involving the kidney. "Considering that we did not observe any major changes in the mRNA levels of moesin and ezrin in the human kidney cancers, we decided to analyze the TCGA data set for the presence of potential mutations on moesin and ezrin." (PMID 34503512, 2021). "Interestingly, the expression levels of neither moesin nor ezrin were altered in a statistically significant manner in any of the kidney cancer types." (PMID 34503512, 2021).
lupus nephritis (1 paper, 2021). Glomerulonephritis in the context of systemic lupus erythematosus. "This suggests that moesin is a target glomerular antigen in lupus nephritis." (PMID 33669337, 2021).
malaria (1 paper, 2017). Malaria is a serious and sometimes fatal disease caused by a parasite that commonly infects a certain type of mosquito which feeds on humans. "Therefore, the capability of moesin to translocate to the cell surface upon Plasmodium GPI stimulation as well as the impact of moesin-deficiency on malaria PAMP-mediated cytokine induction and phagocytosis of P. berghei was analyzed in vitro." (PMID 28560184, 2017). "Since the TNF response induced by malaria PAMPs was generally low and variable for both WT and moesin-deficient cells, potential differences in TNF secretion may not be detectable in this experimental setting." (PMID 28560184, 2017). "After clearly establishing the binding of moesin to Pf GPI we next sought to determine the physiological relevance of this interaction in the context of malaria." (PMID 28560184, 2017). "In good agreement with previous observations in BMDM, the LPS- and malaria PAMP-induced response of BMDC revealed subtle and inconsistent differences between WT and moesin-deficient BMDC for all conditions tested." (PMID 28560184, 2017). "Moreover, we reasoned that moesin may play a role in the immune response to Plasmodium infection via its ability to interact with Plasmodium GPI as well as in malaria pathology due to its ability to modulate immunological synapse and endothelial paracellular gap formation." (PMID 28560184, 2017). "Using synthetic GPI affinity chromatography, we have identified the host protein moesin as an interaction partner of P. falciparum GPI and further addressed the functional relevance of this interaction in the development of malaria pathology." (PMID 28560184, 2017). "We report here that despite the interaction between Pf GPI and moesin in vitro, moesin does not translocate to the cell surface in response to malaria PAMP in human and murine macrophages." (PMID 28560184, 2017). "Collectively, our findings demonstrate that even though Plasmodium GPI and moesin interact, the relevance of this interaction in the context of malaria pathology could not be established." (PMID 28560184, 2017). "We report here that although moesin and Plasmodium GPI interact in vitro, moesin is not critically involved in processes leading to Plasmodium-induced pro-inflammatory immune responses or malaria-associated cerebral pathology." (PMID 28560184, 2017). "Additionally, moesin may be involved in key events leading to the development of malaria pathology independent of its interaction with Plasmodium GPI, since moesin was described to be relevant in immunological synapse formation and in endothelial permeability." (PMID 28560184, 2017). "Although malaria PAMP other than GPI were present in the schizont extracts used here, which could activate pattern recognition receptors independent of moesin, we observed minor cytokine secretion and subtle induction of cytokine transcription in both wild type and moesin-deficient BMDM and BMDC." (PMID 28560184, 2017).
meningitis (1 paper, 2019). A disorder characterized by acute inflammation of the meninges of the brain and/or spinal cord. "Together, our findings suggest that SEZ meningitis depends on BifA, a Fic-domain protein that manipulates moesin-dependent signaling to modulate BBB permeability." (PMID 31071198, 2019). "Collectively, our findings reveal that SEZ meningitis depends on BifA, a Fic-domain protein that disrupts BBB function by manipulating moesin-dependent signaling." (PMID 31071198, 2019).
metastatic cancers (1 paper, 2020). A carcinoma which has spread from the original site of growth to another anatomic site. "Finally, immunohistochemistry results demonstrated that p-Moesin was overexpressed in primary and metastatic cancers." (PMID 33292278, 2020).
muscular dystrophy (1 paper, 2023). Muscular dystrophy (MD) refers to a group of more than 30 genetic diseases characterized by progressive weakness and degeneration of the skeletal muscles that control movement. "The identification of moesin as a target for intervention in muscular dystrophy strengthens our findings, linking the PGA-VAS-related RA-pEV proteins to our data on chronic fatigue." (PMID 38274452, 2023).
neutropenia (1 paper, 2024). A decrease in the number of neutrophils found in the blood. "Although repeated infections in early life are a common clinical presentation of X-MAID, we reported a case of adult-onset profound neutropenia and hemizygous MSN deletion with no history of significant childhood infections, cytopenias, or hypogammaglobulinemia." (PMID 39781543, 2024). "Despite repeated infections in early life being a common clinical presentation of X-MAID, we report a case of adult-onset profound neutropenia with no history of significant childhood infections, cytopenias, or hypogammaglobulinemia, in which a hemizygous deletion of the MSN gene was detected." (PMID 39781543, 2024).
osteoarthritis (1 paper, 2023). A noninflammatory degenerative joint disease occurring chiefly in older persons, characterized by degeneration of the articular cartilage, hypertrophy of bone at the margins and changes in the synovial membrane. "Four target genes (LMNA, MSN, PDCD6IP, and GAPDH) with five miRNAs (hsa-let-7a-5p, hsa-let-7b-5p, hsa-mir-15a-5p, hsa-mir-26a-5p, and hsa-mir-23b-3p) were associated with the pathway in osteoarthritis according to the results of the miRNet network analysis." (PMID 38132172, 2023).